FGF21 (fibroblast growth factor 21)
Diseases named in the same sentence as FGF21 in open-access papers (continued):
Sharing a sentence is not in itself a finding about the gene and the disease.
breast carcinoma (17 papers, 2013 to 2026). "In this context, high FGF-21 levels at the time of breast cancer diagnosis have been associated with reduced survival, and a decrease in its serum concentration has been reported after one year of endocrine therapy." (PMID 40806072, 2025). "Conversely, FGF21 deficiency is associated with an increased risk of liver, prostate, clear cell renal cell carcinoma, and breast cancer." (PMID 38784036, 2024). "To further investigate the association between FGF21 expression and breast cancer prognosis, we grouped 157 breast cancer patients into low or high-FGF21 expression subsets." (PMID 38238320, 2024). "In fact, certain adipokines, like TNF-α, MCP-1, and Fibroblast Growth Factor (FGF)-21 have been directly implicated in the progression of breast cancer." (PMID 31244777, 2019). "Additionally, FGF21 deficiency was associated with an increased risk of prostate cancer, clear cell renal cell carcinoma and breast cancer." (PMID 39744501, 2025). "In our study, we showed that FGF21 promotes resistance to DOX in mammary tumor cells, indicating that FGF21 may be implicated in the chemoresistance of breast cancer." (PMID 38238320, 2024). "Furthermore, we observed overexpression of FGF21 in tumor tissues from breast cancer patients, which was associated with poor prognosis." (PMID 38238320, 2024). "In breast cancer patients, FGF-21 has been proposed as a potential biomarker for early diagnosis and prognosis." (PMID 40806072, 2025). "Both peritumoral and systemic administration of FGF21 promoted breast cancer tumor growth, while FGF21 knockout attenuated the tumor-promoting effects of the high-fat diet." (PMID 38238320, 2024). "Mechanistically, exogenous FGF21 treatment enhanced the anti-apoptotic ability of breast cancer cells through STAT3 and Akt/FoXO1 signaling pathways, and mitigated doxorubicin-induced cell death." (PMID 38238320, 2024). "To study the effects of elevated systemic or hepatic FGF21 on breast cancer, we utilized an allograft breast cancer animal model by transplanting E0771 cells into C57BL/6J mice, followed by peritumoral injection of recombinant mouse FGF21." (PMID 38238320, 2024). "Previous studies have shown higher serum levels of FGF21 in the early stages of breast cancer, but these levels decreased in patients treated with hormones." (PMID 38238320, 2024). "In summary, our study provides evidence that the increased expression of hepatic FGF21 in HFD-induced NAFLD promotes the progression of breast cancer by enhancing the anti-apoptotic abilities of breast cancer cells." (PMID 38238320, 2024). "In conclusion, our findings suggest that FGF21 promotes the anti-apoptotic ability of breast cancer cells via Akt and STAT3 pathways." (PMID 38238320, 2024). "In this study, we investigated the impact of NAFLD on breast cancer tumor growth and cell viability through the potential mediator, hepatic fibroblast growth factor 21 (FGF21)." (PMID 38238320, 2024). "To determine the source of FGF21 and its impact on breast cancer, we established an in vitro conditioned medium-based system." (PMID 38238320, 2024). "We have observed overexpression of FGF21 in breast cancer tissues, and patients with high FGF21 levels show poorer prognoses." (PMID 38238320, 2024). "The caspase family activity test indicated that FGF21 inhibited DOX-induced breast cancer cell apoptosis via both extrinsic and intrinsic pathways." (PMID 38238320, 2024). "As expected, both the Annexin V assay and the TUNEL assay confirmed that simultaneous administration of FGF21 effectively mitigated DOX-induced breast cancer cell apoptosis." (PMID 38238320, 2024). "Our clinical data further emphasized the overexpression of FGF21 in breast cancer and its prognostic value." (PMID 38238320, 2024). "To assess the clinical relevance of FGF21 in breast cancer, we analyzed the expression of FGF21 in different molecular types of tumor samples along with paired adjacent normal tissues (PNTAT)." (PMID 38238320, 2024).
breast carcinoma (continued). "As with M-CSF, breast cancer cells also produce FGFs, including FGF-21, as well as expressing the FGFR1, thereby enabling autocrine tumor cell proliferation." (PMID 35677046, 2022). "Although the primary role of FGFR4 in metabolism occurs in hepatocytes, its ablation results in a net inhibitory effect on mammary tumour progression, most likely due to suppressing signals triggered by FGF21 from breast adipocytes." (PMID 35193394, 2022). "Our results are similar to two recent in vivo studies that found hepatic FGF21 expression was activated, and serum FGF21 levels were increased in response to hepatocarcinogenesis, breast cancer, primary renal tumors, and papillary thyroid cancer." (PMID 33753729, 2021). "Several studies have reported increased serum levels of FGF21 in various human cancers, including clear cell renal cell carcinoma and breast cancer." (PMID 31408968, 2019). "Thus the mechanisms underlying the delay of TGFα-driven breast cancer development by the FGFR4 deficit may be related to metabolic activities of FGF21/19 that cause systemic metabolic programming that in turn impacts local metabolic, and therefore, cellular effects such as the decrease in mitoses." (PMID 24279986, 2013). "They suggest novel roles of FGF21 signaling and metabolic reprogramming in suppressing mammary tumors that rise from luminal epithelial cells in the ducts and lobules surrounded mostly by FGF21-responsive adipocytes." (PMID 24279986, 2013). "Furthermore, in an in vitro NAFLD model using FGF21 KO hepatocytes, the promoting effects on breast cancer cell viability were lost." (PMID 38238320, 2024). "Additionally, we provide the first report on the expression profile and prognostic value of FGF21 in breast cancer patients." (PMID 38238320, 2024). "Interestingly, we observed comparable tumor-promoting effects with peritumoral FGF21 administration, suggesting the significant impact of pathological levels of systemic FGF21 on breast cancer." (PMID 38238320, 2024). "Additionally, we used primary hepatocytes from both wild-type and FGF21 knockout mice to emphasize the importance of FGF21 in the NAFLD–breast cancer axis." (PMID 38238320, 2024). "Limited data are available regarding the role of FGF21 in breast cancer." (PMID 38238320, 2024). "This indicates that FGF21 may have broad applicability as a clinical marker in breast cancer." (PMID 38238320, 2024). "FGF21 acts through its obligatory receptors FGFR and co-receptor β-Klotho, which were found to be expressed and responsive to FGF21 treatment in breast cancer cell lines." (PMID 38238320, 2024). "Like M-CSF, both FGF-21 and GDF-15, as described in the current study, have been reported to be significantly elevated in the blood of female breast cancer patients, albeit based on very limited prior data." (PMID 35677046, 2022). "In multiple cases of breast cancer, including TNBC, the receptor for FGF-21 is upregulated, suggesting a role for the growth factor in the development of the disease." (PMID 31244777, 2019). "Increased FGF21 levels were observed in patients with liver tumor, non-small cell lung cancer, breast cancer, clear renal cell carcinoma and endometrioid carcinoma." (PMID 39744501, 2025). "On the other hand, the increased tumor growth observed in FGF21 knockout mice suggests that FGF21 is not the sole mediator involved in high-fat diet-induced breast cancer progression." (PMID 38238320, 2024). "Even though the activities of FGF21 in these types of cancers have not been explored yet, elevated serum levels of FGF21 were reported in the early stages of breast cancer 106 but significantly reduced following 12 months of hormonal therapy." (PMID 36263162, 2022). "However, in our study, we did not observe significant effects of FGF21 on the migration of breast cancer cell lines." (PMID 38238320, 2024).
cardiomyopathy (17 papers, 2017 to 2025). A disease of the heart muscle or myocardium proper. "Pathway enrichment revealed key susceptibilities to developing cardiomyopathies and ischemia due to FGF21 deficiency during fasting, which was potentially mitigated by rhFGF21 treatment." (PMID 40998786, 2025). "The results indicated that FGF21 deficiency enhanced T2DM-induced cardiomyopathy characterized by cardiac dysfunction, remodeling, and myocardial morphological abnormalities." (PMID 29445083, 2018). "Recent research has revealed that FGF21 could play an important role in cardiac pathological remodeling effects and prevention of cardiomyopathy; however, the underlying mechanism remains largely unknown." (PMID 37156793, 2023). "Compared to wild-type mice, chronic alcohol-reared FGF21-knockout mice exhibit metabolic abnormalities such as cardiac damage and cardiac dysfunction, indicating that FGF21 is a protective agent against alcohol-induced cardiomyopathy." (PMID 38069273, 2023). "The depletion of FGF21 generates significant cardiomyopathy in mice, which provokes widespread cardiac dysfunction and subsequent induction of a decline in the global longitudinal strain and ejection fraction." (PMID 38069273, 2023). "Fibroblast growth factor 21 (FGF21), galectin-3 and copeptin have been proposed as biomarker candidates to detect the early stages of cardiomyopathy." (PMID 34573919, 2021). "Plasma FGF-21 levels were high in PA patients before they developed long-term complications, both before severe complications (such as lethal cardiomyopathy) and before milder complications (prolonged QT interval and slight left ventricular hypertrophy)." (PMID 30159853, 2018). "Case 8 had initially highly elevated plasma FGF-21 levels in stable conditions, which decreased over the years until the patient died due to lethal cardiomyopathy." (PMID 30159853, 2018). "Next, we focused on dissecting the protective mechanism of FGF21 against T2DM-induced cardiomyopathy." (PMID 29445083, 2018). "In summary, we confirmed that FGF21 induces preventive effect on T2DM-induced cardiomyopathy characterized by improving cardiac function, suppressing cardiac remodeling, and apoptosis." (PMID 29445083, 2018). "And this pathway also participates in FGF21-induced prevention on T2DM cardiomyopathy observed in the present study, indicating that inhibition of cardiac apoptosis contributes to the prevention of FGF21 on DCM." (PMID 29445083, 2018). "The aim of this study was to investigate the possible protective effects of FGF21 against DOX-induced cardiomyopathy." (PMID 28837153, 2017). "In addition, of note, FGF21 has been shown to protect cardiomyopathy by inflammatory pathway, oxidative stress, AMP-activated protein kinase pathway and lipid-lowering effect." (PMID 39182099, 2024). "The increase of FGF-21 correlated with the onset of cardiomyopathy." (PMID 38667723, 2024). "Similarly, experimental evidence showed the cardioprotective effects of Fibroblast growth factor 21 (FGF21) against DOXO-induced cardiomyopathy via activation of SIRT1/LKB1/AMPK axis." (PMID 34081265, 2021). "In addition, FGF21 prevents type-2 diabetic lip toxicity-induced cardiomyopathy through activation of the antioxidant pathway effect in the hearts of mice." (PMID 34777697, 2021). "Moreover, the protective effects of FGF21 on cardiomyopathy have been attributed to activation of AMPK." (PMID 31178962, 2019). "Therefore, in the present study, the effect of FGF21 on T2DM-induced cardiomyopathy was investigated." (PMID 29445083, 2018). "In addition, the autocrine action of FGF21 in the heart is stimulated by cardiomyopathy." (PMID 36594101, 2023). "Therefore, in the present study, we investigated whether this pathway is also required in FGF21-induced prevention on cardiomyopathy in T2DM mice." (PMID 29445083, 2018).
depression (17 papers, 2019 to 2026). "We found that FGF21 and FMI together had significant mediating effects on the association between depression and any respiratory symptoms; the total proportion of mediation through all paths with FGF21 and fat max index was 18.3%." (PMID 39523673, 2024). "The associations between FGF19 and FGF21 levels and clinical symptom scores of the total population, HCs, and patients with depression were analyzed separately." (PMID 37266540, 2023). "Changes in FGF21 following valproate treatment for bipolar depression in bipolar II disorder were associated with Hamilton Depression Rating Scale (HDRS) scores, with individuals having increased FGF21 showing worse outcomes as measured by HDRS scores." (PMID 35017468, 2022). "In conclusion, depression is associated with higher levels of FGF21 compared to healthy controls and those with lower levels of FGF21 (25th percentile of the sample) in the context of normal-weight BMI seem to have improved depression severity over time." (PMID 35017468, 2022). "Lower levels of cerebrospinal fluid FGF21 have been associated with higher Beck Depression Inventory scores." (PMID 35017468, 2022). "We further examined the effects of overexpression of FGF21 using adeno‐associated virus (AAV) vectors on depression‐like behaviours in wild‐type and FGF21‐deficient mice." (PMID 34472154, 2021). "The roles of endogenous FGF21 in the control of water intake, body weight, food intake and anxiety‐related or depression‐like behaviour in response to social defeat stress were then examined using FGF21‐deficient mice." (PMID 34472154, 2021). "FGF21‐deficient mice in the present study showed augmented depression‐like behaviour, suggesting inhibitory actions of FGF21 on depression‐like behaviour." (PMID 34472154, 2021). "In the present study, FGF21‐deficient animals showed augmented depression‐like behaviour induced by social defeat stress, suggesting anti‐depressant actions of endogenous FGF21." (PMID 34472154, 2021). "A limited number of studies have explored the association between depression and FGF21." (PMID 39523673, 2024). "After adjusting for potential confounders, such as BMI and smoking, and correcting for multiple testing, four proteins remained significantly associated with depression: fibroblast growth factor 21 (FGF21), FGF19, Interleukin-6 (IL-6) and Interleukin-20 receptor subunit alpha (IL-20RA)." (PMID 39523673, 2024). "Are changes in depression severity associated with baseline FGF21 in the context of BMI?" (PMID 35017468, 2022). "We then examined whether endogenous FGF21 modulated depression‐like behaviours by analysing social defeat stress‐induced depression‐like behaviours in FGF21‐deficient mice." (PMID 34472154, 2021). "FGF21‐deficient mice showed augmented depression‐related behaviours after social defeat stress." (PMID 34472154, 2021). "This study aimed to investigate the role of FGF19 and FGF21 in MDD and to explore the possible pathogenic mechanism of metabolic and cognitive dysregulation in depression." (PMID 37266540, 2023). "The finding that FGF21 was higher in individuals with MDD is somewhat in contrast to previous research showing that lower levels of CSF FGF21 were associated with higher BDI scores in Chinese men, but not women, and without official diagnosis of depression." (PMID 35017468, 2022). "We further identified HNMT as a depression risk factor, FGF21 as an RA risk factor, MME as a depression protective factor, and platelet count/FGF21/HNMT as shared factors using Mendelian randomization." (PMID 42317795, 2026). "The attenuated change in depression severity in those normal-weight participants with higher FGF21 does suggest that some aspect of FGF21 signaling is perpetuating depressive symptoms." (PMID 35017468, 2022).
depression (continued). "The findings showed that depression score was positively correlated with the severity of SCAD, and that serum FGF21, β-klotho, mBDNF, and proBDNF levels were linked to depressive symptoms in SCAD patients." (PMID 34163381, 2021). "In the current study, the effects of recombinant human FGF21 (rhFGF21) on the depression-like behaviors of LPS-induced mice models were evaluated." (PMID 32184729, 2020). "With this in mind, the present study aimed to clarify the relationship between FGF21, β-klotho, mBDNF, and proBDNF and SCAD with comorbid depression, in addition to also exploring the underlying mechanisms of these disease processes." (PMID 33584362, 2020). "Currently, among the twenty-two identified FGFs, FGF2, FGF9, FGF21, and FGF22 have been found to be associated with depression." (PMID 30804785, 2019). "In a recent study, the FGF21 levels in cerebrospinal fluid were found negatively related to the score of Beck Depression Inventory (BDI) in male subjects." (PMID 30804785, 2019). "Lower levels of FGF21 in the cerebrospinal fluid (CSF) was associated with higher scores on the Beck Depression Inventory in Chinese men, but not women, who were not diagnosed with a mood disorder." (PMID 35017468, 2022). "Interestingly though, those with normal BMI and lower FGF21 levels showed a reduction in depression severity over time compared to all other groups." (PMID 35017468, 2022). "A previous study indicated that muscle mass could influence depression by secreting myokines, including irisin and FGF21, which are supposed to mediate depression." (PMID 35144536, 2022). "FGF21 has been previously examined in depression and bipolar disorder in small studies." (PMID 35017468, 2022). "Identification of the interaction between FGF21, BMI, and depression improvement over time suggests that FGF21 is important for people with MDD, who have a lower BMI, but for obese patients other mechanisms may be related to treatment outcomes." (PMID 35017468, 2022). "Participants with lower BMI, classified as normal weight, and lower FGF21 being in the 25th percentile of the sample had a greater decrease in depression severity as measured by the HAMD-17 compared to those with higher FGF21 being in the 75th percentile of the sample." (PMID 35017468, 2022). "It remains unclear whether endogenous or exogenous FGF21 modulates psychological stress‐induced depression‐like behaviours." (PMID 34472154, 2021). "Furthermore, administration of FGF21 has been reported to reduce lipopolysaccharide‐induced depression‐like behaviours in mice, although FGF21 has also been reported to induce anxiety‐related behaviour." (PMID 34472154, 2021). "Chronic disturbed circadian rhythm and high glucocorticoid levels have been shown to exert deteriorating effects on depression status, which might have obscured possible anti‐depressant actions of FGF21 in the present study." (PMID 34472154, 2021). "Furthermore, Liu and coworkers demonstrated a significant negative correlation between the level of FGF21 in cerebrospinal fluid and depression in male subjects, suggesting that FGF21 has beneficial effects on neuroprotection and emotional regulation." (PMID 33584362, 2020). "The lower the FGF21 levels were, the more severe the depression was." (PMID 30804785, 2019). "There is evidence from mouse models that endogenous FGF-21 counteracts depression-like behaviour so that higher FGF-21 levels might reflect a compensatory response but these data are difficult to extrapolate to depression in humans." (PMID 39799156, 2025). "Moreover, a previous study reported a significant negative association between cerebrospinal fluid FGF21 levels and Beck Depression Inventory (BDI) scores in male Chinese subjects, but not in female." (PMID 32184729, 2020). "Recent studies have indicated that fibroblast growth factor 21 (FGF21) plays an important role in the processes of CHD and depression." (PMID 33584362, 2020).